HGD (homogentisate 1,2-dioxygenase)
Diseases named in the same sentence as HGD in open-access papers (continued):
Sharing a sentence is not in itself a finding about the gene and the disease.
malignant glioma (1 paper, 2023). A grade III or grade IV glioma arising from the central nervous system. "In this study, based on the perspective of tyrosine metabolism, we found that the tyrosine metabolizing enzymes 4‐hydroxyphenylpyruvate dioxygenase (HPD), homogentisate 1,2‐dioxygenase (HGD), and fumarylacetoacetate hydrolase (FAH) were upregulated in more malignant glioma patients." (PMID 37786553, 2023).
osteosarcoma (1 paper, 2012). A usually aggressive malignant bone-forming mesenchymal neoplasm, predominantly affecting adolescents and young adults. "Western blotting with anti-HGD antibodies confirmed the presence of HGD in human both normal and AKU chondrocytes, synoviocytes, osteoblasts as wells in human osteosarcoma cells." (PMID 22105303, 2012).
thyroid cancer (1 paper, 2025). "In addition to TFF3, other markers such as homogentisate 1,2-dioxygenase (HGD1) and ADM3, a member of the adrenomedullin family, are also recognized for their involvement in thyroid cancer biology, albeit with less clarity regarding their specific roles." (PMID 40346322, 2025).
infection (2 papers, 2019 to 2023). The state of being infected such as from the introduction of a foreign agent such as serum, vaccine, antigenic substance or organism. "qPCR expression analysis of GhHPPD and HGD gene showed that in leaf and petiole tissues the expression was increased with the infection time." (PMID 31644543, 2019). "We found that the HPPD and HGD gene (c52132_g1; c55425_g1) in tyrosine metabolism pathway were up-regulated after infection." (PMID 31644543, 2019). "In an alternative approach, HGA could be utilised via innovative gene silencing techniques, employing a transient knock down of the homogentisate 1,2-dioxygenase gene in vivo using siRNA, temporarily increasing HGA systemically during an acute infection." (PMID 37443717, 2023).
tumor (2 papers, 2021 to 2022). "Up to now, there are few reports on the association between EIF5A2, HGD, HS6ST1, PLS1, PTHLH, and YEATS2 methylation modification and tumor." (PMID 34796198, 2021). "Mechanistically, we found that decreased HGD and GSTZ1 promote aerobic glycolysis in KIRC, coordinate the balance of amino acid metabolism and energy metabolism in tumor cells, and ultimately activate the tumor cell cycle and tumor progression." (PMID 35562974, 2022). "More importantly, this is the first report of the amino acid metabolizing enzymes HGD and GSTZ1 as tumor biomarkers." (PMID 35562974, 2022). "In summary, we identified the tyrosine metabolizing enzymes HGD and GSTZ1 as biomarkers of KIRC, which will further the understanding of the tumor metabolism profile, provide novel strategies and theoretical support for diagnosing and treating KIRC and as referential for future clinical research." (PMID 35562974, 2022). "In this study, we have found that HGD and GSTZ1 regulate the level of fumarate by metabolizing tyrosine, and by affecting GOT1 and GOT2 to coordinate amino acid metabolism and energy metabolism, determine the energy production pathway of tumor cells, and ultimately regulate the cell cycle." (PMID 35562974, 2022).
autosomal recessive disease (1 paper, 2022). Autosomal recessive form of disease. "AKU in an ultra-rare autosomal recessive disease caused by the mutations of the Homogentisate 1,2- dioxygenase (HGD) gene which leads to a deficiency of the HGD enzyme producing accumulation of the unprocessed toxic catabolite homogentisic acid (HGA), especially in connective tissues." (PMID 39086980, 2022).
carcinoma (1 paper, 2013). A malignant tumor arising from epithelial cells. "mSAs-HGD and carcinomas, however, stained uniformly positive for pErk." (PMID 23845441, 2013).
HGD also shares sentences with these, for which no sentence is quoted: metabolic disorder (12 papers); genetic disorder (5); amyloidosis (2); osteoarthropathy (2); chronic granulomatous disease (1); cutaneous disorder (1); melasma (1); skin aging (1); viral infections (1).